AHR (aryl hydrocarbon receptor)
Diseases named in the same sentence as AHR in open-access papers (continued):
Sharing a sentence is not in itself a finding about the gene and the disease.
mastitis (continued). "Supplementation with a Lactobacillus reuteri (L. reuteri) strain with the capacity to produce AhR ligands also improved E. coli-induced mastitis in an AhR-dependent manner." (PMID 34297785, 2021). "Collectively, these results suggest that AhR activation alleviates E. coli-induced mastitis by improving tight junction protein expression and limiting NF-κB pathway activation." (PMID 34297785, 2021). "To investigate the potential effects of the AhR pathway in regulating mastitis, we treated mice with Ficz, a classical agonist of AhR, followed by E. coli stimulation." (PMID 34297785, 2021). "Overall, these results suggest the role of intestinal microbiota in the pathogenesis of mastitis through regulating AhR activation by metabolizing tryptophan into key active molecules." (PMID 34297785, 2021). "In this study, we found that AhR activation using Ficz ameliorated mastitis symptoms, which were related to limiting NF-κB activation and enhancing barrier function." (PMID 34297785, 2021). "In this study, we determined microbiota-mediated aryl hydrocarbon receptor (AhR) activation alleviated E. coli-induced mastitis in mice." (PMID 34297785, 2021). "To study the correlation between AhR activation and mastitis development, we first detected the AhR protein level in the mammary glands of mice with E. coli-induced mastitis." (PMID 34297785, 2021). "Our study showed that intestinal dysbiosis impairs mammary gland AhR activation, initiates mice mastitis, as well as exacerbates E. coli-induced mastitis." (PMID 34297785, 2021). "Similarly, formononetin alleviated LPS-induced mastitis symptoms by enhancing the integrity of the lactation barrier and suppressing AhR-Src signaling pathway activation." (PMID 40901059, 2025). "Moreover, the AHR activated by Lactobacillus reuteri helps alleviate Escherichia coli-induced mastitis in mice." (PMID 37942478, 2023). "Indeed, treating mice with L. reuteri alleviates E. coli-induced inflammation and barrier injury, while inhibiting AhR activation reverses L. reuteri’s effects, suggesting that L. reuteri regulates mastitis development by producing AhR agonists." (PMID 34297785, 2021). "In addition, administering the L. reuteri strain alleviated E. coli-induced mastitis in an AhR-dependent manner." (PMID 34297785, 2021). "We investigated whether AhR activation by microbiota-metabolic ligands could influence mastitis development in mice." (PMID 34297785, 2021). "However, our results do not allow us to determine whether the restoration of the epithelial barrier integrity by AhR activation is a response to inflammation limitation in the context of mastitis." (PMID 34297785, 2021). "To investigate whether intestinal microbiota mediates the tryptophan metabolism, regulating AhR activation and mastitis pathogenesis, in addition to possibly improving mastitis outcomes by dietary consumption, we treated mice with tryptophan with or without ABX, followed by E. coli stimulation." (PMID 34297785, 2021). "We then tested whether impaired AhR activation contributes to E. coli-induced mastitis." (PMID 34297785, 2021). "However, whether impaired AhR activation by intestinal dysbiosis contributes to the immunopathology of mastitis remains to be explored." (PMID 34297785, 2021). "To investigate the crosstalk between intestinal microbiota mediated AhR signaling and mastitis, we disrupted the intestinal microbiota by administering a cocktail of antibiotics (ABX) and then detected the AhR activation." (PMID 34297785, 2021). "In this study, we found IPA could increase the expression of AhR and AhR inhibitor reversed the anti-inflammatory role of IPA on S. aureus-induced inflamamtion, suggesting IPA protected mice against mastitis through activating AhR." (PMID 41170435, 2025).
mastitis (continued). "Specifically, antibiotic-induced gut dysbiosis depletes commensal bacteria such as Clostridium and Lactobacillus reuteri and impairs the production of SCFAs and indole derivatives, which limit pathogen-induced mastitis by inhibiting HDAC3 and activating AhR, respectively." (PMID 41139776, 2025).
Parkinson disease (10 papers, 2017 to 2025). A progressive degenerative disorder of the central nervous system characterized by loss of dopamine producing neurons in the substantia nigra and the presence of Lewy bodies in the substantia nigra and locus coeruleus. "We further show that carbidopa, an FDA-approved drug for Parkinson's disease as well as an AhR agonist, inhibits IDO1 expression in PDAC cells." (PMID 35997090, 2022). "In contrast, several phytochemicals, such as tangertin, a citrus flavonoid, as well as natural compounds (Withanolide A, Withaferin A) from Withaferin Sominifera plants, act through AhR to protect against Parkinson’s symptoms in several models of PD." (PMID 34685709, 2021). "It should be noted that AhR is activated by carbidopa, which is used to treat Parkinson’s disease." (PMID 35743162, 2022). "An experimental murine model of Parkinson’s disease has revealed that AhR activation by BaP may have a protective effect against this pathology." (PMID 35743162, 2022).
schizophrenia (10 papers, 2018 to 2025). A major psychotic disorder characterized by abnormalities in the perception or expression of reality. "We surmise that the aberrant activation of the aryl hydrocarbon receptor by toxins derived from gut microbes or the environment drives premature cellular and neuronal senescence, a hallmark of schizophrenia." (PMID 38892092, 2024). "Dysfunction of hippocampal GABAergic interneurons have been recently associated with schizophrenia; interestingly, a post-mortem proteomic study on human schizophrenic patients identified AhR signaling as one disrupted function of their hippocampus." (PMID 30149528, 2018). "Wider immune dysregulation in schizophrenia may therefore be intimately linked to AhR and α7nAChR regulation, with consequences for mitochondrial function and intercellular interactions." (PMID 40729204, 2023). "It will be important for future research to determine how the mitochondrial presence of AhR, TrkB, and α7nAChR modulate core mitochondrial function and patterned gene expression, and thereby the changes in intercellular fluxes evident in schizophrenia." (PMID 40729204, 2023). "Based on the hypothesis presented here, we discuss alternative schizophrenia interventions, including AhR antagonists, mitochondrial transplant, membrane lipid replacement, and recombinant human IL-22." (PMID 39596179, 2024). "Since oxidative stress is higher in patients diagnosed with schizophrenia, beneficial effects of clozapine treatment might also result from AhR signaling." (PMID 34979820, 2022). "Notably, AhR and α7nAChR are present on the mitochondrial membrane, indicating that direct effects on mitochondria, and therefore on core aspects of cellular function, are likely to be important aspects of pathophysiological alterations in schizophrenia." (PMID 40729204, 2023). "Moreover, proteomic pathway analysis revealed an altered AhR pathway in the hippocampus of people diagnosed with schizophrenia suggesting that an interaction of clozapine might contribute to its antipsychotic activity." (PMID 34979820, 2022).
Anxiety (9 papers, 2011 to 2025). Intense feelings of nervousness, tension, or panic often arise in response to interpersonal stresses. "Indole–AhR signaling supports serotonergic and glutamatergic balance and dampens microglial activation, thereby constraining anxiety-like behavior and depressive affect; loss of indole producers removes this brake on excitatory tone and neuroinflammation." (PMID 41244880, 2025). "PCB decreased zone crossings in poor-affinity–AHR mice and increased them in high-affinity–AHR mice, suggesting that PCB causes increased anxiety in high-affinity–AHR mice." (PMID 21571617, 2011). "The AHR phenotype caused opposite effects in response to PCBs, slightly increasing anxiety in poor-affinity–AHR mice (fewer head dips) and slightly decreasing anxiety in high-affinity–AHR mice." (PMID 21571617, 2011). "Reduced levels of indole-producing microbes are frequently observed in anxiety and depression, suggesting that impaired indole–AhR signaling contributes to disease pathology and may be restored through microbiome-targeted interventions." (PMID 41244880, 2025). "Moreover, microbiota metabolites, such as 4-hydroxyphenylpropionic, 4-hydroxyphenylacetic acid, and caffeic acid, can activate AHR to modulate the Th17/Treg imbalance, strengthening resistance to stress-induced anxiety- and depressive-like behaviors." (PMID 39655201, 2024). "Genes like CACNA1C (calcium regulation) and AHR (inflammation) may influence pain pathways, while NOTCH3 is involved in immune responses and stress regulation, and anxiety may contribute to pain modulation." (PMID 39940809, 2025).
candidiasis (9 papers, 2019 to 2024). Infection with the organism Candida. "The presence of compound 14 in the animal organism acts as immunomodulatory by stimulating the production of IL-22 via the aryl hydrocarbon receptor (AhR), promoting IL-18 expression, and providing protection against Candida infection." (PMID 37111503, 2023). "Administration of the microbial metabolite indole-3-aldehyde, known to stimulate the production of IL-22 via the aryl hydrocarbon receptor (AhR), promoted IL-18 expression and protection against Candida infection." (PMID 31681274, 2019). "As a ligand of aryl hydrocarbon receptor (AhR), IAld induces the production of IL-22, thereby providing a protection against candidiasis and mucosal damage." (PMID 31349604, 2019). "Icld could promote the production of IL-22 via interaction with AHR, inducing the expression of IL-18 to inhibit Candida infection." (PMID 34361945, 2021). "For this purpose, we evaluated the expression of genes downstream of AhR, such as cytochrome P450 family 1 subfamily A member 1 (Cyp1a1) and subfamily B member 1 (Cyp1b1) and Il22 in the lungs and colons of mice with aspergillosis and candidiasis, respectively." (PMID 38534388, 2024). "Because indole-3-lactate can act as a ligand for AhR, we speculate that L. crispatus may regulate the IL-22-AhR response in the vagina, reducing the risk of vaginal candidiasis in the same way IAld does, and potentially activating the AhR response in newborns to prevent early-life candidiasis." (PMID 32843557, 2020).
cleft palate (9 papers, 2011 to 2025). Cleft palate is a fissure type embryopathy that affects the soft and hard palate to varying degrees. "The AhR antagonist α-naphthoflavon has also been reported to exert a preventive effect on the TCDD-induced cleft palate." (PMID 35745180, 2022). "In conclusion, quercetin reduces the development of TCDD-induced cleft palate in mice by inhibiting CYP1A1 via AhR." (PMID 35745180, 2022). "Previous studies have suggested the efficacy of vitamins and AhR antagonists in preventing the development of a cleft palate." (PMID 35745180, 2022). "Cleft lip and palate are among the most frequently diagnosed congenital diseases, and exposure to 2,3,7,8-tetrachlorodibenzo-p-dioxin (TCDD) during pregnancy induces cleft palate via AhR." (PMID 35745180, 2022). "In conclusion, our results suggest that quercetin reduces the development of TCDD-induced cleft palate by inhibiting CYP1A1 through AhR." (PMID 35745180, 2022). "Genetic ablation of AhR results in the complete suppression of TCDD-induced cleft palate, demonstrating an indispensable role of AhR in the pathogenesis." (PMID 30708991, 2019). "Consistent with the results of the BXD PheWAS, a matched PheWAS in humans using BioVU links rs2066853 in AHR with cleft palate (P=0.012; logistic regression)." (PMID 26833085, 2016). "Further elucidation is needed to determine whether activation of genes other than CYP1A1 is involved in cleft palate, or whether it is due to an unknown pathway other than transcriptional activation mediated by AhR." (PMID 35745180, 2022). "AhR is involved in the development of the cleft palate attributed to TCDD." (PMID 35745180, 2022). "Exposure to dioxin, an exogenous AhR ligand, causes disease conditions, such as cleft palate and hydronephrosis, in Ahr+/+ mice but not Ahr−/− mice, showing that AhR is required for induction of dioxin toxicity." (PMID 33963922, 2021). "For example, cleft palate can be induced by triazoles (antifungal organochlorine insecticides) through CYP 26-mediated RAR activation, while cleft palate induced by dioxin (environmental contaminant) is an AhR-mediated event, which also is likely to involve the retinoid system." (PMID 32171711, 2020). "It was suggested that quercetin antagonizes TCDD and binds to AhR, thereby contributing to the prevention of TCDD-induced cleft palate." (PMID 35745180, 2022). "Our results indicate that atRA-activated RARG controls the expression of AHR at GD10.5 in the developing palate, which in turn appears necessary for TCDD to induce cleft palate." (PMID 21807577, 2011). "Specifically, TeCDD exposure evoked tissue lesions and teratogenicity, such as cleft palates and hydronephrosis, in wild type (Ahr+/+) mice but not in Ahr−/− mice, indicating the pivotal role of AHR and its downstream signaling in dioxin toxicity." (PMID 40711040, 2025). "AhR is reported to be involved in the development of TCDD-induced cleft palate because AhR knockout mice do not develop cleft palate when TCDD is administered to them." (PMID 35745180, 2022). "AhR is thought to be involved in the development of TCDD-induced cleft palate, since AhR knockout mice do not develop cleft palate when TCDD is administered to them." (PMID 35745180, 2022). "Exposure of dioxins to pregnant mice can induce fetal malformations such as hydronephrosis and cleft palate without severe toxicity to the dams, and these teratogenic effects are dependent on AhR expression." (PMID 26405201, 2016). "In addition, even though quercetin can markedly suppress the AhR activity of TCDD in vitro, it does not completely prevent cleft palate in vivo." (PMID 35745180, 2022). "Together, our findings that a) RARG, but not RARA, is mandatory for TCDD to induce cleft palate and b) RAR directly controls Ahr gene expression imply that the AHR-expressing cells at the origin of the malformation are necessarily distributed within the domain where RARG is operational." (PMID 21807577, 2011).
oral squamous cell carcinoma (9 papers, 2018 to 2025). "A possible role for the AhR in this important pathway was suggested by our previous studies showing that the AhR regulates CD274/PD-L1 expression in oral squamous cell carcinomas." (PMID 40449595, 2025). "The overexpression of NCOA7 promotes the proliferation of oral squamous cell carcinoma cells by activating the aryl hydrocarbon receptor (AHR)." (PMID 37511343, 2023). "In an oral squamous cell carcinoma model, tumor cell- and immune cell-expressed AhR collaborated to promote tumor immune evasion with AhR knockout in tumor cells restoring anti-tumor immunity." (PMID 36588678, 2022). "Consequently, AhR antagonism increases sensitivity to cisplatin, decreases tumor sphere formation, and reduces xenograft tumor growth in oral squamous cell carcinoma." (PMID 38807762, 2024). "AhR also modulates the tumor microenvironment of oral squamous cell carcinoma." (PMID 38807762, 2024). "Similarly, exposure of oral squamous cell carcinoma cells to the supernatants from Pseudomonas aeruginosa and Porphyromonas gingivalis, the latter commonly found in the oral cavity, induced AhR activity and augmented expression of ALDH1, a marker associated with chemoresistance." (PMID 38807762, 2024). "AhR also plays a central role in IFNγ-induced expression of IDO1, PD-L1, CTLA-4, LAG-3, and CD39 in an oral squamous cell carcinoma model." (PMID 38632994, 2024). "Consistent with this, AHR antagonist CB7993113 suppressed tumor growth and increased overall survival in vivo in an oral squamous cell carcinoma mouse model." (PMID 30501068, 2018).
plaque psoriasis (9 papers, 2022 to 2026). "Tapinarof is a non‐steroidal, topical, aryl hydrocarbon receptor (AhR) agonist, which has been approved by the US Food and Drug administration for the treatment of plaque psoriasis." (PMID 39150292, 2024). "Tapinarof, an AhR agonist, is a recently FDA approved non‐steroidal topical treatment for plaque psoriasis." (PMID 36226669, 2022). "Tapinarof (an AhR modulator) and roflumilast (a PDE-4 inhibitor) have exhibited favorable efficacy and safety outcomes and have been approved by the FDA for the topical treatment of plaque psoriasis." (PMID 38399292, 2024). "Although dioxin is linked to serioustoxicological issues, activation of the AhR may not be per se undesiredas, only recently, the AhR agonist Tapinarof was approved for thetreatment of plaque psoriasis." (PMID 36459434, 2022).
renal cell carcinoma (9 papers, 2019 to 2025). "In renal cell carcinoma (RCC) patients, gut microbiota‐derived tryptophan metabolites are significantly associated with AhR and E‐cadherin expression in RCC." (PMID 40103267, 2025). "In the context of renal cell carcinoma, the study investigated the impact of AhR on EMT development." (PMID 38361941, 2024). "It has recently been described that aryl hydrocarbon receptor (AhR) activation mediates kidney disease and renal cell carcinoma." (PMID 32443455, 2020). "In conclusion, AF and 5F 203 represent experimental anticancer agents that target novel molecular targets pertinent to renal cell carcinoma: AhR, CYP 1A1 and CYP 2W1." (PMID 32443455, 2020). "Nevertheless, the CYP1B1 finding, that acts as a well-known oncogenic protein in renal cell carcinoma by the Aryl Hydrocarbon Receptor Signaling suggested an unexplored link between aberrant Complement activation, DNA damage and tumorigenesis." (PMID 31284268, 2019). "The AHR is mostly expressed in the nucleus of advanced clear cell renal cell carcinoma (RCC) and tumor infiltrating lymphocytes, and its expression is related to the stage and histological grade of pathological tumors." (PMID 36668758, 2022). "It has been demonstrated that AhR is mainly expressed in the nuclei of advanced clear cell renal cell carcinoma (RCC) and tumour-infiltrating lymphocytes, and its expression correlates with the stage of the pathological tumour and the histological grade." (PMID 31488157, 2019). "The upregaulted gene ARNT is invovled in Hypoxia Signaling in the Cardiovascular System, Renal Cell Carcinoma Signaling, VEGF Signaling, HIF1α Signaling, Aryl Hydrocarbon Receptor Signaling and Xenobiotic Metabolism Signaling pathways." (PMID 33272211, 2020). "As expected, AHR is the most enriched pathway in this analysis, followed by pathways of oxidative stress, renal cell carcinoma, Hippo and non-Hippo, ATM dependent DNA damage, and lipid metabolism for LDL, HDL and TG." (PMID 37151890, 2023).
type 1 diabetes (9 papers, 2010 to 2025). "As such, AHR signaling has been recognized as a key regulator of several immune diseases, however, current literature regarding the impact of AHR activation on the pathogenesis of type 1 diabetes suggests that its effect is indirect through immune modulation and not directly on beta cells." (PMID 35757772, 2022). "While the AHR signaling pathway has been reported to play a pivotal role in health and disease, the role of bacterial extracellular vesicles as inducers of AHR nuclear translocation has not been previously reported in the context of type 1 diabetes." (PMID 35757772, 2022).